CXCL8 (C-X-C motif chemokine ligand 8)
Diseases named in the same sentence as CXCL8 in open-access papers (continued):
Sharing a sentence is not in itself a finding about the gene and the disease.
autism (24 papers, 2011 to 2025). Persistent deficits in social interaction and communication and interaction as well as a markedly restricted repertoire of activity and interest as well as repetitive patterns of behavior. "Additionally, cytokines such as IFN-γ, TGF-β, RANTES, and CXCL8 were also elevated in the plasma/serum of subjects with autism, with IFN-γ likely produced by CD4+ T cells and natural killer (NK) cells." (PMID 39337983, 2024). "Further research with larger cohorts is warranted to conclusively determine the implications of CXCL8, IL-6, and TNF-alpha in early childhood autism." (PMID 39337983, 2024).
colon adenocarcinoma (24 papers, 2013 to 2025). "Besides, a recent study identified CXCL3 and CXCL8 as diagnostic and prognostic genes in colon adenocarcinoma via integrating mRNA expression and DNA methylation profiles." (PMID 33330065, 2020). "It has been suggested that patients with colon adenocarcinoma with high CXCL8 expression have a worse prognosis." (PMID 37954103, 2023). "Earlier studies indicated that the expression of CXCL3 and CXCL8 in colon adenocarcinoma tissue increased significantly when compared with normal tissue." (PMID 33489879, 2020). "CXCL3 and CXCL8 are the key genes that affect the diagnosis and prognosis of colon adenocarcinoma." (PMID 35802745, 2022). "In colon adenocarcinoma, CXCL1, CXCL2, and CXCL3 negatively correlated with EMT, while CXCL5, CXCL6, PPBP, and CXCL8 positively correlated with EMT." (PMID 37686093, 2023). "For example, in colon adenocarcinoma, the expression of CXCL1, CXCL2, and CXCL3 negatively correlated with EMT, whereas the expression levels of CXCL5, CXCL6, PPBP, and CXCL8 positively correlated with EMT." (PMID 37686093, 2023).
bipolar disorder (23 papers, 2015 to 2025). A disorder of the brain that causes unusual shifts in mood, energy, activity levels and the ability to carry out day-to-day tasks. "CXCL8 mRNA was increased in high inflammation bipolar disorder compared to low inflammation subgroups (63–78%, p < 0.025)." (PMID 34911938, 2021). "Duration of illness also negatively correlated with CXCL8 mRNA in bipolar disorder." (PMID 34911938, 2021).
head and neck cancer (23 papers, 2016 to 2026). A primary or metastatic malignant neoplasm affecting the head and neck. "High CXCL8 expression was associated with poor overall survival in head and neck cancer patients." (PMID 41800238, 2026). "The head and neck cancer patients’ salivary cytokines that were assessed by the studies, along with photobiomodulation therapy, included IL-12p70, TNF-α, IL-6, IL-8, IL-10, CXCL8, and IL-1β." (PMID 38792366, 2024).
SARS-CoV infection (23 papers, 2005 to 2025). "In additional cell-based studies, SARS-CoV infection induced expression of CXCL8 and CCL2 in A549 lung epithelial cells and THP-1 monocytic cells." (PMID 33613280, 2020). "However, some genes were downregulated during SARS-CoV infection, including those for inflammatory cytokines like CXCL8, and genes involved in immune responses such as AHNAK." (PMID 38681774, 2023). "Lung autopsies of SARS patients and in vitro SARS-CoV infections of macrophages and alveolar and bronchial cells have clearly demonstrated upregulation of numerous monocyte/macrophage, neutrophil and T cell-specific chemokines, including CCL2, CCL5, CXCL8, CXCL9 and CXCL10." (PMID 33613280, 2020).
skin inflammation (23 papers, 2013 to 2026). "In skin inflammation, keratinocytes produce VEGF and CXCL-8/IL-8, which play crucial roles." (PMID 39765834, 2024).
Hepatic steatosis (22 papers, 2013 to 2025). Steatosis is a term used to denote lipid accumulation within hepatocytes. "Noteworthy, peripheral blood neutrophils from patients with NASH produced approximately 30% more CXCL8 than those from patients with hepatic steatosis or controls." (PMID 40794228, 2025). "CXCL-8 (also known as IL-8), another chemokine known to increase with the development of hepatic steatosis, is also involved in immunosuppression via MDSCs and TAMs recruitment, and contributes to the formation of TIME." (PMID 37266440, 2023). "Most clinical studies have reported higher circulating CXCL8 in NASH compared to hepatic steatosis or non-NAFLD." (PMID 40794228, 2025). "In terms of non-invasive diagnosis, CXCL8 has been incorporated in a combined index termed “NAFLD discriminant score”, together with adiponectin, TNF-α, and visfatin, to distinguish NASH from hepatic steatosis with a sensitivity and specificity of 90% and 66%, respectively." (PMID 40794228, 2025).
Infertility (22 papers, 2009 to 2026). "In fact, CXCL8 expression in these tissues is repressed when E2 levels are elevated and excessively high levels of CXCL8 correlate with infertility." (PMID 19440537, 2009).
pulpitis (22 papers, 2016 to 2025). Inflammation of the dental pulp. "Pulpitis is characterized by the production of high levels of pro-inflammatory cytokines including TNFα, IL-4, IL-6, IL-8, IL-10 and CXCL8." (PMID 35902880, 2022). "Our results demonstrated IL-6, TNF-α TNF, IL-1β, CXCL8 and CCL2 are closely related to the immune infiltrating cells in pulpitis." (PMID 37179325, 2023). "IL-6, TNF-α, IL-1, CXCL8, and CCL2 may be essential molecule of the immune response regulation network in pulpitis." (PMID 37179325, 2023). "Gene expression profiles and bioinformatics analysis confirmed that M0 macrophages and neutrophils play an irreplaceable role in pulpitis immunity, and the critical genes in the immune reaction to pulpitis are suggested to be IL-6, TNF-α, IL-1β, CXCL8, and CCL2." (PMID 37179325, 2023). "In addition to investigating the possible regulatory mechanisms of DEGs, we screened key genes as biomarker candidates for the diagnosis of pulpitis, including PTPRC, CD86, CCL2, IL6, TLR8, MMP9, CXCL8 and ICAM1." (PMID 33046027, 2020). "Therefore, IL-6, TNF-α, IL-1β, CXCL8, and CCL2 may participate in the occurrence and development of pulpitis by regulating the corresponding immune cells, which needs further experimental verification." (PMID 37179325, 2023).
cystitis (21 papers, 2009 to 2024). Inflammation of the urinary bladder. "We previously demonstrated a link among clinical fluoroquinolone susceptible E. coli reducing in vitro urothelial interleukin-8 (CXCL8) induced by E. coli K-12, polymicrobial cystitis, and pyuria absence." (PMID 34361936, 2021). "Previous studies of urine chemokine levels have mainly focused on IL-6 and CXCL-8 during episodes of symptomatic cystitis." (PMID 20016852, 2009). "Previously, we found correlations among polymicrobial cystitis and fluoroquinolone susceptible UPEC and their ability to reduce CXCL8 among those cytokines when induced in vitro by the non-pathogen E. coli-K12 strain." (PMID 34361936, 2021).
diabetic nephropathy (21 papers, 2009 to 2025). "For example, urinary and serum levels of CXCL8/IL8 are elevated in diabetic kidney disease, and CXCL1 has been described to be associated with interstitial fibrosis in progressive IgA nephropathy." (PMID 34064989, 2021). "Existing studies have reported that inhibition of CXCL8 attenuates high-glucose-induced renal tubular cell-mediated inflammation and apoptosis in diabetic kidney disease." (PMID 40995516, 2025). "Ambinathan and colleagues published a thorough description of the relationship between renal function and urinary and serum inflammatory markers, including CXCL8, in a large cohort of patients with diabetic nephropathy." (PMID 40718478, 2025). "It was observed that a CXCL8 antagonist ameliorates diabetic nephropathy in diabetic male mice and attenuates high glucose-induced mesangial injury." (PMID 34367469, 2021).
epilepsy (21 papers, 2009 to 2025). A brain disorder characterized by episodes of abnormally increased neuronal discharge resulting in transient episodes of sensory or motor neurological dysfunction, or psychic dysfunction. "In comparison, CXCL8 expression is increased in the brain of patients with epilepsy which suggests its role is similar to that of KC in mouse epilepsy." (PMID 35457023, 2022). "The role of CXCL1, a murine ortholog of the human chemokine CXCL8 (IL-8), and its receptors CXCR1 and CXCR2 in epilepsy was discussed in a previous study using a murine model." (PMID 40243443, 2025).
Fever (21 papers, 2009 to 2026). Body temperature elevated above the normal range. "All in all, the present study has identified IFN-α as a universal biomarker of human OROV fever, while CXCL8 & IL-5 and CXCL10 & IL-17 were observed consistently in early and late seroconverters, respectively." (PMID 31784575, 2019). "The results showed that OROV fever patients presented higher levels of CXCL8 and IFN-α (pink background) and lower levels of TNF and IL-10 than HD (blue background), regardless of antibody profile at baseline." (PMID 31784575, 2019). "Regardless immunoglobulin profile, all OROV fever patients presented higher levels of CXCL8, and IFN-α and lower levels of TNF and IL-10 at baseline as compared to healthy donors (HD)." (PMID 31784575, 2019). "Elevated IL-8 (CXCL8) level results in only transient pyrexia and less pathogen bacteria shedding of Salmonella-infected pigs while increased TNF-α level can lead to prolonged inflammatory condition and persistent pathogen shedding." (PMID 30718974, 2019).
keloid (21 papers, 2014 to 2025). An irregularly shaped, elevated mark on the skin caused by deposits of excessive amounts of collagen during wound healing. "Chemokines such as CCL2 (monocyte chemoattractant protein‐1) and CXCL8 (IL‐8) are highly expressed by keloid fibroblasts and keratinocytes and promote immune cell recruitment and sustained inflammation." (PMID 41049267, 2025). "Among the DEGs involved in the IL-13 signaling pathway identified by the KEGG analysis, CXCL8 was recently confirmed to play an important role in keloid scar formation." (PMID 35082796, 2021). "We showed that interleukin-8 (IL-8), also known as CXCL8, is elevated in keloids and patients' circulation." (PMID 39081787, 2024). "We also examined secretion of a previously established wound healing mediator panel (CCL2, IL-6, CXCL8, VEGF, HGF and CCL27), which showed reduced HGF secretion in the reconstructed keloid model compared to the normal skin model." (PMID 31187196, 2019).
leukocytosis (21 papers, 2012 to 2026). "Tissue damage outside of the liver induces leukocytosis due to the strong upregulation of hepatic CXCL8/IL8 gene expression and the effect of serum IL8 on bone marrow." (PMID 35336843, 2022). "The case for milk CXCL8 is particularly dubious, as its concentration was hardly augmented at 8 hpi when a substantial increase in milk neutrophil concentration has already occurred, and the correlation between CXCL8 and concentration and milk leukocytosis was low." (PMID 23696826, 2013). "Of note, in these patients, the percentage of CXCL8-secreting CD34+ cells correlated with the degree of reticulin fibrosis and leukocytosis, hinting that CXCL8 secretion may serve as a biomarker for the presence of significant bone marrow fibrosis and a more aggressive disease." (PMID 37760903, 2023). "CXCL8 concentrations declined sharply as soon as 16 hpi, in contrast with the concentrations of IL-17A and IFN-γ in quarters infused with ovalbumin alone or with LPS, which were low at 8 hpi, peaked at 16 hpi and thus augmented after the onset of milk leukocytosis." (PMID 27100324, 2016).
parasitic infection (21 papers, 2011 to 2024). "CXCL8 might, therefore, aggravate late-phase reactions by enhanced inflammatory cell recruitment to the sites of parasitic infection." (PMID 26870962, 2016). "Decreased TLR expression and elevated CXCL8 secretion may represent possible mechanisms for aggravation of allergic symptoms in case of parasitic infection." (PMID 26870962, 2016). "We demonstrated that even in the absence of symptomatic infections or asymptomatic urinary or parasitic infections, children with CZS have low CCL2 and CXCL8 production and increased serum levels of IFNγ and IL-13." (PMID 37766239, 2023). "It was shown that TLR4 or TLR9 stimulation combined with FcεRI activation by anti-IgE resulted in a synergistic increase of IL-4, CXCL8, IL-13 and RANTES/CCL5, all of which are thought to enhance IgE-mediated responses, such as allergy or parasitic infection." (PMID 26870962, 2016).
Peri-Implantitis (21 papers, 2015 to 2026). An inflammatory process with loss of supporting bone in the tissues surrounding functioning DENTAL IMPLANTS. "They discovered the involvement of inflammation-promoting fibroblasts and a predominance of CXCL8+ fibroblast-CXCR2+ neutrophil interactions in peri-implantitis compared to periodontitis, underlining the enhanced host response in peri-implantitis." (PMID 40486514, 2025). "In the present study, our results showed that the proinflammatory cytokines IL-6, IL-1β, and CXCL8 were upregulated in peri-implantitis." (PMID 34931168, 2021). "Finally, the potential target genes, namely, IL-6, TLR4, FN1, IL-1β, CXCL8, MMP-9, and SPP1, were found to be associated with peri-implantitis, and our results were consistent with those of previous studies." (PMID 34931168, 2021). "The intersecting genes, including IL6, TLR4, FN1, IL1β, CXCL8, MMP9, and SPP1, were revealed as potential genetic biomarkers and target genes of peri-implantitis." (PMID 34931168, 2021). "This study provides supportive evidence that IL6, TLR4, FN1, IL1β, CXCL8, MMP9, and SPP1 might be used as potential target biomarkers for peri-implantitis which may provide further therapeutic potentials for peri-implantitis." (PMID 34931168, 2021). "We found that IL-6, TLR4, FN1, IL-1β, CXCL8, MMP-9, and SPP1 might be used as potential biomarkers for the diagnosis of peri-implantitis." (PMID 34931168, 2021).
chronic rhinosinusitis (19 papers, 2010 to 2025). Chronic form of sinusitis. "A recent study suggested that patients with elevated levels of CXCL8/IL-8 often have difficult-to-treat chronic rhinosinusitis." (PMID 38550710, 2024).
osteoporosis (19 papers, 2014 to 2025). A condition of reduced bone mass, with decreased cortical thickness and a decrease in the number and size of the trabeculae of cancellous bone (but normal chemical composition), resulting in increased fracture incidence. "Adefovir causes increased bone loss in patients by binding to LCN2, while CXCL8, a specific target of tenofovir, interferes with the expression of CXLC8, and patients ultimately experience adverse events of osteoporosis." (PMID 40687725, 2025). "Based on these findings, we speculate that CXCL8 and CCL20 may play a role in generalized osteoporosis during systemic inflammation in which serum levels of CXCL8 and CCL20 are elevated." (PMID 26103626, 2015). "Based on our findings, we created a pathophysiological model illustrating how CXCL8 and CCL20 might influence bone remodeling in inflammatory conditions and contribute to osteoporosis." (PMID 26103626, 2015).
pulmonary TB (19 papers, 2005 to 2025). "In conclusion, our current study recommends prospective clinical evaluation of the biomarkers identified herein given that others have previously linked the association of CXCL8 and MCP-1 levels with pulmonary TB." (PMID 37992019, 2023). "Knockdown of NRF by NRF siRNA augmented the mRNA synthesis and protein release of both IP-10/CXCL10 and IL-8/CXCL8 from PBMC of active pulmonary TB patients with high bacterial load." (PMID 24223729, 2013). "Levels of IP-10/CXCL10 and IL-8/CXCL8 mRNA were higher in AM from patients with AFB-high active pulmonary TB (9.8±1.9, p<0.01 and 0.3±0.2, p<0.01, n = 6, respectively) than those of normal subjects (0.3±0.1 and 0.1±0.01, n = 8, respectively)." (PMID 24223729, 2013). "Up-regulation of NRF in the PBMC of active pulmonary TB patients with high bacterial load is associated with increased occupancy of NRF at the IP-10/CXCL10 and IL-8/CXCL-8 promoters and decreased the synthesis of corresponding mRNA." (PMID 24223729, 2013). "Serum levels of CCL2, CXCL8 and TNFα were measured in patients with pulmonary tuberculosis (N = 12), extra-pulmonary tuberculosis (N = 8) and BCG-vaccinated healthy volunteers (N = 12)." (PMID 16001981, 2005). "Previous studies have shown that in vivo (circulating) serum levels of IFNγ, IL-10, TNFα, CXCL8 and IL-6 are raised in pulmonary tuberculosis." (PMID 16001981, 2005). "We determined circulating levels of CCL2, CXCL8 and TNFα in sera of pulmonary and extra-pulmonary tuberculosis patients and controls." (PMID 16001981, 2005). "The levels of CXCL8 were found elevated in pulmonary TB patients." (PMID 35153741, 2021). "CXCL8 is the main granulocyte chemoattractant and has been shown to be elevated in supernatants of macrophages and in bronchoalveolar lavage from patients with pulmonary TB." (PMID 32754123, 2020). "The levels of IP-10/CXCL10 and IL-8/CXCL8 mRNA from PBMC were significantly higher in patients with AFB-high active pulmonary TB (0.2±0.1, n = 6, p<0.01 and 3.0±0.8, n = 6, p<0.001, respectively) as compared with normal subjects (0.001±0.001 and 0.3±0.1, n = 8, respectively)." (PMID 24223729, 2013). "Previous literature showed that the expression of CXCL8 and CXCL9 in the serum of patients with active pulmonary tuberculosis is elevated and returns to normal levels after 4–6 months of treatment." (PMID 36992931, 2023). "We delineate the role of NRF in pulmonary TB, which inhibits the expressions of IP-10/CXCL10 and IL-8/CXCL8 in AM and PBMC of patients with high bacterial load." (PMID 24223729, 2013). "We have now demonstrated that NRF is upregulated in the circulating monocytes and AM of patients with active pulmonary TB, and modulates synthesis and release of IP-10/CXCL10 and IL-8/CXCL8." (PMID 24223729, 2013). "Our results indicate a pathophysiological role of NRF in repression of IP-10/CXCL10 and IL-8/CXCL8 synthesis by AM and PBMC in active pulmonary TB." (PMID 24223729, 2013). "The up-regulated release of IP-10/CXCL10 and IL-8/CXCL8 in patients with active pulmonary TB was suppressed by specific NF-κB inhibitor JSH-23, suggesting both IP-10/CXCL10 and IL-8/CXCL8 release is mediated through NF-κB activation." (PMID 24223729, 2013). "Patients with active pulmonary TB had a higher serum level of IP-10/CXCL10 (392.2±70.5 pg/ml, n = 19) and IL-8/CXCL8 (31.9±8.5 pg/ml, n = 19) than that of normal subjects (62.8±5.4 pg/ml; 4.5±.0 pg/ml, n = 15, p<0.01, respectively)." (PMID 24223729, 2013). "In summary, we demonstrated that NRF, for the first time in human disease, is up-regulated in the PBMC and AM of active pulmonary TB patients with high bacterial load to repress MTb induced IP-10/CXCL10 and IL-8/CXCL8 synthesis and protein release." (PMID 24223729, 2013). "Circulating levels of chemokines CXCL8, CCL2 and RANTES are raised in bronchoalveolar lavage fluid (BALF) and alveolar macrophages from pulmonary tuberculosis patients." (PMID 16001981, 2005).
pulmonary TB (continued). "CXCL8 concentration was found to be elevated in fatal TB, increases in CCL2 were observed with disseminated and meningeal TB, and TGF-β increased in extrapulmonary TB in children compared to pulmonary TB." (PMID 32377537, 2020). "Increased release of chemokines, including IL-8/CXCL8, IP-10/CXCL10, MIG/CXCL9 and MCP-1/CCL2, has been observed in monocytes, alveolar macrophages and polymorphonuclear granulocytes in patients with pulmonary TB compared to healthy subjects." (PMID 24223729, 2013). "Patients with AFB-low active pulmonary TB had a higher level of IL-8/CXCL8 mRNA (0.2±0.03, n = 6, p<0.05), but not IP-10/CXCL10 mRNA (0.5±0.2, n = 6) than normal subjects." (PMID 24223729, 2013). "Patients with AFB-low active pulmonary TB had a higher level of IP-10/CXCL10 mRNA (0.05±0.03, n = 6, p<0.01), but not IL-8/CXCL8 (0.5±0.2, n = 6) than normal subjects." (PMID 24223729, 2013).